ANGPTL2 (angiopoietin like 2)
Diseases named in the same sentence as ANGPTL2 in open-access papers (continued):
Sharing a sentence is not in itself a finding about the gene and the disease.
osteosarcoma (18 papers, 2013 to 2026). A usually aggressive malignant bone-forming mesenchymal neoplasm, predominantly affecting adolescents and young adults. "We next examined the underlying molecular mechanism of high levels of ANGPTL2 secretion in osteosarcoma." (PMID 32082485, 2020). "ANGPTL2 has been shown to cause osteosarcoma metastasis in prior studies." (PMID 36476230, 2022). "We previously demonstrated that ANGPTL2 promotes tumor progression in some cancers, such as breast cancer, lung cancer, and osteosarcoma, via α5β1 integrin." (PMID 37452654, 2023). "In fact, we previously reported that ANGPTL2 promotes tumor angiogenesis in skin cancer and osteosarcoma." (PMID 37452654, 2023). "In osteosarcoma models, tumor-secreted pro-inflammatory glycoprotein angiopoietin-like protein 2 (ANGPTL2) binding to integrin α5β1 mediates tumor cell intravasation via MMPs, enhancing lung metastasis." (PMID 37350937, 2023). "We previously demonstrated that TFE3 chimeric proteins induce expression of angiopoietin‐like protein 2 (ANGPTL2), a secretory protein that accelerates tumor progression in some cancers, such as lung, breast and colorectal cancers, and osteosarcoma." (PMID 37452654, 2023). "Our study strongly suggests that tumor-secreted ANGPTL2 initiates programs that lead to neutrophil recruitment within the lung, a process essential for the lung colonization in spontaneous models of osteosarcoma pulmonary metastasis." (PMID 32082485, 2020). "Together, results generated from our studies will have an impact not only in osteosarcoma, but other tumors in which ANGPTL2 signaling is known to be deregulated." (PMID 32082485, 2020). "We found that serum levels of ANGPTL2 in osteosarcoma patients are significantly higher compared to those in healthy controls and that ANGPTL2 secretion by tumor cells plays an essential role in osteosarcoma metastasis." (PMID 32082485, 2020). "Other soluble factors, such as IL-8 and ANGPTL2 have been additionally shown to mediate osteosarcoma metastatic progression and PMN formation in different mouse models." (PMID 33233625, 2020). "We demonstrated that ANGPTL2 played a vital role in the progression of osteosarcoma metastasis by inducing pre-metastatic lung formation and extravasation." (PMID 32082485, 2020). "To interrogate the role of ΔNp63 in ANGPTL2 regulation in osteosarcoma, we first utilized our OS17-shΔNp63 and OS25-ΔNp63 cell lines expressing high or low basal levels of this gene." (PMID 32082485, 2020). "Collectively, our data suggest that ANGPTL2 alters vascular endothelial cell-cell adhesion to permit extravasaion of osteosarcoma cells in the lung." (PMID 32082485, 2020). "We further determined that ΔNp63, an oncogenic isoform of p63, drives ANGPTL2 gene expression and its subsequent secretion from the osteosarcoma cells." (PMID 32082485, 2020). "Here, we report that ANGPTL2 secretion is elevated in osteosarcoma patients when compared to healthy donors." (PMID 32082485, 2020). "Together, these results demonstrated that ΔNp63 drives ANGPTL2 expression via NF-κB binding site in osteosarcoma." (PMID 32082485, 2020). "The ANGPTL2 protein promotes migration and metastasis of osteosarcoma cells by promoting tumor cell intravasation mediated by the integrin α5β1, p38MAPK, and MMP proteins." (PMID 29389861, 2018). "Most importantly, ANGPTL2 role as driver of metastases was demonstrated in lung, breast and liver cancer and in osteosarcoma cell lines." (PMID 29389861, 2018). "In contrast, hypomethylation of ANGPTL2 promoter has been observed in human osteosarcoma cell lines, proportionally with the increase in ANGPTL2 expression and progression of the disease when these cells were injected in mice." (PMID 27101308, 2016). "In human osteosarcoma cells, angiopoietin-like protein 2 (ANGPTL2) appears to interact with integrin α5β1 to promote p38 activation and MMP9 expression, which favors invasiveness." (PMID 27200351, 2016).
osteosarcoma (continued). "More recently, silencing the expression of ANGPTL2 in osteosarcoma cell lines delayed the occurrence of lung metastases when injected in nude mice by reducing the expression of MMP9." (PMID 25360865, 2015). "Here we report that ANGPTL2 expression shows circadian rhythmicity in various mouse tissues and in synchronized human osteosarcoma cells." (PMID 23469106, 2013). "Recently, a study found that ANGPTL2 could enhance angiogenesis in osteosarcoma by upregulating the expression of hexokinase 2 (HK2) and VEGF." (PMID 39252946, 2024). "Interestingly, GDC-0152 attenuated the malignant progression of osteosarcoma promoted by ANGPTL2 via the PI3K/AKT signaling pathway." (PMID 36476230, 2022). "ANGPTL2-induced osteosarcoma was examined in this study for its effect on malignant progression." (PMID 36476230, 2022). "In addition, ANGPTL2 secretion by tumor cells has been demonstrated to recruit neutrophils into the lungs, triggering osteosarcoma lung metastasis." (PMID 34095215, 2021). "Here, we investigated whether lung epithelial cells activated by tumor secreted ANGPTL2 might be essential for primary tumor-induced neutrophil recruitment in lung and for subsequent pre-metastatic niche formation in osteosarcoma." (PMID 32082485, 2020). "Future studies will reveal whether ANGPTL2 in serum acts as a biomarker for osteosarcoma progression." (PMID 32082485, 2020). "In addition, studies have shown that ANGPTL2 is highly expressed in osteosarcoma cells induced by hypoxia / HIF-1α and promotes cell proliferation, invasion, migration and G1 phase arrest." (PMID 33203792, 2020). "Both mRNA and secretion level of ANGPTL2 in osteosarcoma cells depend on ΔNp63 expression." (PMID 32082485, 2020). "We first asked whether high expression of ANGPTL2 in osteosarcoma cell lines correlated with metastatic nodule formation in vivo." (PMID 32082485, 2020). "Osteosarcoma-secreted angiopoietin like 2 (ANGPTL2) was recently demonstrated to recruit neutrophils in pre-metastatic lungs, and Ly6G mediated depletion of these neutrophils resulted in decreased spontaneous metastasis in syngeneic osteosarcoma models." (PMID 33233625, 2020). "Interestingly, we found that ANGPTL2 levels were strikingly elevated in serum from osteosarcoma patients compared to healthy controls." (PMID 32082485, 2020). "Given the known actions of ANGPTL2 and the strong propensity of osteosarcoma for metastasis to lung, we asked whether ANGPTL2 might invole in osteosarcoma metastasis." (PMID 32082485, 2020). "High level of ANGPTL2 expression has also been shown to accelerate pulmonary cancer cell invasion and metastasis through autocrine and paracrine mechanisms, to drive metastasis of human lung cancer, osteosarcoma cell lines, and breast cancer." (PMID 31384179, 2019). "Abundant ANGPTL2 expression is reportedly highly correlated with frequency of carcinogenesis and tumor metastasis in lung cancer, breast cancer, colorectal cancer, and osteosarcoma." (PMID 28043948, 2017). "ANGPTL2 has been shown to be increasingly methylated in ovarian cancer and myelodysplastic syndrome, while ANGPTL2 promoter methylation is decreased in osteosarcoma." (PMID 27101308, 2016). "To further investigate the function of E-boxes in CLOCK/BAML1-mediated ANGPTL2 expression, we initially performed real-time PCR analysis using total RNA extracted from the human osteosarcoma cell line U2OS, a well characterized line used to investigate circadian rhythms." (PMID 23469106, 2013). "Furthermore, our preclinical data suggested that ANGPTL2 signaling might be a potential target for the treatment of osteosarcoma metastasis." (PMID 32082485, 2020). "In addition its role in pre metastatic nice formation, we determined that ANGPTL2 drives a loosening of vascular endothelial tight junctions and adherens junctions, creating openings within the capillary wal that permit the passage of osteosarcoma cells." (PMID 32082485, 2020).
osteosarcoma (continued). "To test the role of ANGPTL2 in metastasis development, we knocked down ANGPTL2 gene expression in highly metastatic mouse (LM9, K7M2) and human (OS17) osteosarcoma cell lines and verified knockdown efficiency by ELISA." (PMID 32082485, 2020). "These monolayers were then exposed to media containing recombinant human ANGPTL2, control media, or media conditioned by either control OS17 osteosarcoma cells or by ANGPTL2-depleted OS17 cells." (PMID 32082485, 2020). "We also identified functional E-boxes in the ANGPTL2 promoter and observed occupancy of these sites by endogenous CLOCK in human osteosarcoma cells." (PMID 23469106, 2013). "They exposed human osteosarcoma cell line SaOS2 cells to recombinant human ANGPTL2 after pre-treating or not treating the cells with GDC-0152." (PMID 36476230, 2022). "We then implanted these osteosarcoma cells (with or without ANGPTL2 knockdown) into the tibia of syngeneic (LM9, K7M2) or SCID mice to generate orthotopic tumors and determined serum levels of ANGPTL2 after 2 weeks." (PMID 32082485, 2020). "We previously reported that ANGPTL2 increases MMP expression and activity in osteosarcoma cells." (PMID 25773070, 2015). "In patients with osteosarcoma, the levels of ANGPTL2, which promotes lung PMN formation, were systemically elevated relative to healthy subjects, thus offering the possibility for intervention to hinder ANGPTL2-mediated signaling and subsequent pro-metastatic effects." (PMID 37350937, 2023). "For example, pharmaceutical inhibition of ANGPTL2 signaling using a non-RGD-based integrin-binding peptide (ATN-161) could be a potential strategy for interfering with lung PMN formation in osteosarcoma, as suggested by preclinical studies." (PMID 37350937, 2023).
lung carcinoma (16 papers, 2013 to 2025). "Levels of ANGPTL2 protein and mRNA expression were also higher in CL1-5 cells than in A549 and CL1-0 cells, implying that ANGPTL2 level is associated with migratory ability in lung cancer cells." (PMID 36917086, 2023). "A study involving the Chinese Han population demonstrated that two SNPs (rs11137037 and rs12674822) in ANGPTL2 are associated with the progression of lung cancer." (PMID 37375208, 2023). "Our results indicate that high levels of ANGPTL2 are positively associated with poor survival and lymph node metastasis in lung cancer." (PMID 36917086, 2023). "Accordingly, patients with lung cancer showing elevated expression of ANGPTL2 in cells within the primary tumor were associated with a reduced disease-free survival after surgical resection." (PMID 25360865, 2015). "Our findings show that ANGPTL2 facilitates VEGF-A-dependent LEC lymphangiogenesis in lung cancer cells and that the integrin α5β1, p38 and NF-κB signaling cascade is involved in ANGPTL2-enhanced promotion of VEGF-A synthesis." (PMID 36917086, 2023). "To examine the effects of ANGPTL2 in lung cancer lymph node metastasis, we measured basal migratory activities of lung cancer cell lines CL1-0, CL1-5, and A549." (PMID 36917086, 2023). "Secondly, although our data strongly suggest that ANGPTL2 promotes VEGF-A-mediated lymphangiogenesis in human lung cancer cells, we cannot exclude the possibility that ANGPTL2 also promotes the activities of other angiogenetic factors." (PMID 36917086, 2023). "In summary, our study indicates that ANGPTL2 promotes VEGF-A synthesis in human lung cancer cells and subsequently facilitates LEC lymphangiogenesis via the integrin α5β1 receptor, p38 and NF-κB signaling." (PMID 36917086, 2023). "Our data showed that the NF-κB inhibitor antagonized ANGPTL2-mediated VEGF-A synthesis in lung cancer cells." (PMID 36917086, 2023). "Transcription factors (NFATc, ATF2, and c-Jun) upregulated in lung cancer aggressive cells, increasing angiopoietin-like protein 2 (ANGPTL2) expression, and cell motility and invasion." (PMID 36476606, 2022). "In human lung cancer cell lines, constitutive overexpression of ANGPTL2 increased in vitro motility and invasive capacity, and accelerated metastasis and shortened mice survival in in vivo xenograft models." (PMID 25360865, 2015). "ANGPTL2 was expressed in lung cancer cells (around 68% of cells in a typical positive sample expressed ANGPTL2) and in stromal cells (around 75% of were ANGPTL2+ cells)." (PMID 26056041, 2015). "Mechanistic analyses indicated that ANGPTL2 binds LILRB2 to support the growth of lung cancer cells and that the SHP2/CaMK1/CREB axis controls the proliferation of lung cancer cell lines." (PMID 26056041, 2015). "Recently, we reported that the F4 construct (containing −168 to +98 of human ANGPTL2) exhibits very high reporter activity in human lung cancer cells." (PMID 23469106, 2013). "Similarly, IHC data confirmed upregulated expression of ANGPTL2 in lung cancer tissue, while TCGA data revealed significant associations between high levels of ANGPTL2 expression and regional lymph node metastasis." (PMID 36917086, 2023). "Upregulation of ANGPTL2 indicates a poor prognosis with reduced survival in lung cancer patients." (PMID 36917086, 2023). "Thus, ANGPTL2 enhances VEGF-A synthesis in lung cancer cells via integrin α5β1, p38 and NF-κB signaling." (PMID 36917086, 2023). "The adipokine angiopoietin-like protein 2 (ANGPTL2) regulates tumor progression and metastasis, although the functions of ANGPTL2 in lung cancer are unknown." (PMID 36917086, 2023). "Abnormally high levels of ANGPTL2 have been found in lung cancer cells and serum from patients with colorectal or gastric cancer, with evidence showing that upregulated ANGPTL2 expression promotes the growth, drug resistance and metastasis of colorectal cancer." (PMID 36917086, 2023).
lung carcinoma (continued). "Thus, ANGPTL2 is a promising therapeutic target for treating lung cancer progression and metastasis." (PMID 36917086, 2023). "Next, we examined whether ANGPTL2 regulates lung cancer lymphangiogenesis in tumor xenograft mouse models." (PMID 36917086, 2023). "In addition, ANGPTL2 is constitutively expressed in adipocytes and secreted by lung cancer cells, prostate cancer cells, and peritoneal cells, where it has topical effects." (PMID 28934245, 2017). "Our data suggest that ANGPTL2 is a powerful driver of metastasis in lung cancer." (PMID 26056041, 2015). "Thus, ANGPTL2 is a promising therapeutic object for treating lung cancer." (PMID 36917086, 2023). "Importantly, ANGPTL2 promoted lung cancer growth and lymphangiogenesis in vivo." (PMID 36917086, 2023). "Thus, ANGPTL2 is a more important adipokine than others in lung cancer progression." (PMID 36917086, 2023). "In addition, ANGPTL2 has reported to enhance the progression and metastasis of lung cancer." (PMID 36917086, 2023). "The adipokine angiopoietin-like protein 2 (ANGPTL2) promotes tumor growth and VEGF-A-dependent lymphangiogenesis via integrin α5β1, p38 MAP kinase (MAPK), and NF-κB signaling in human lung cancer." (PMID 41511312, 2025). "In current report, we found higher levels of ANGPTL2 and LYVE-1 (a LEC marker) expression in lung cancer tissue than in normal control tissue." (PMID 36917086, 2023). "However, the regulating effects of ANGPTL2 upon lymphangiogenesis remain unknown in lung cancer." (PMID 36917086, 2023). "Our mouse xenograft model revealed that ANGPTL2 overexpression promotes the upregulation of LYVE-1 and VEGF-A expression in lung cancer tissue." (PMID 36917086, 2023). "ANGPTL2 is known to promote cell proliferation, metastasis, and EMT in lung cancer, breast cancer, hepatocellular carcinoma, and pancreatic ductal adenocarcinoma." (PMID 35768842, 2022). "Our results suggest that signaling involving ANGPTL2 and LILRB2 is important for lung cancer development and represents a novel target for treatment of this type of cancer." (PMID 26056041, 2015). "In this study, we provide evidence that both ANGPTL2 and LILRB2 are often expressed in lung cancer tissue and play important roles in the proliferation and survival of cancer cells." (PMID 26056041, 2015). "Notably, treatment with VEGF-A reversed ANGPTL-2 shRNA-induced reductions in LEC tube formation and migration, implying that ANGPTL2 facilitates VEGF-A-dependent lymphangiogenesis in lung cancer cells." (PMID 36917086, 2023). "Interestingly, we recently found that the human ANGPTL2 minimal promoter (−168 to +98) also contains a putative CRE site essential for ANGPTL2 expression and that ATF2 binds to this site in human lung cancer cells." (PMID 23469106, 2013).